IL2 (interleukin 2)
Diseases named in the same sentence as IL2 in open-access papers (continued):
Sharing a sentence is not in itself a finding about the gene and the disease.
tumor (continued). "IL-2 secretion from activated NK cells plays a crucial role in antitumor activity as it recruits other immune cells to inflammatory sites and enhances the proliferation and cytotoxicity of NK cells during co-culture with tumor cells." (PMID 38890285, 2024). "Similarly, in murine models, sTIM3 reduced anti-tumor cytotoxic T lymphocyte activity, the number of TILs, and the expression of Th1 cytokines IL-2, IFN-γ, and TNF-β." (PMID 38822401, 2024). "Importantly, recent data suggest that CD25 expression on CD8+ T cells is required for native IL-2 to induce effective anti-viral and anti-tumor CD8+ T cell responses." (PMID 39114660, 2024). "Additionally, it was shown that RUX was able to reduce PD-L1 expression in HS-5 stromal cells and increase the cytotoxic effects of T cells on MM tumor cells in a co-culture of IL-2 stimulated T-cells with MM BMMCs." (PMID 38319731, 2024). "We believe that IL-2 may have a role in the dual function of IL-18 in tumor immunity, and further in-depth study is needed." (PMID 39372416, 2024). "Both GLUT1OE CARs demonstrated marked increases in tumor induced IL-2 and IFNγ secretion." (PMID 39370422, 2024). "This hypothesis is supported by the proportional increase in IL-2 secretion as CD8 T cell percentage increases during tumor-targeting therapy." (PMID 39317690, 2024). "However, a phase I clinical trial of anti-PSMA CAR-T reported that IL-2 also has a significant role in tumor destruction." (PMID 38892913, 2024). "High doses of IL-2 have induced anti-tumor immune responses in select cancer patients." (PMID 38928150, 2024). "Conversely, cytokines such as IL-2 and IL-12 can enhance the anti-tumor effects of CAR T cells." (PMID 38789450, 2024). "However, IL-2 therapy presents certain obstacles, primarily stemming from its capacity to activate Tregs, which in turn can dampen the effectiveness of anti-tumor immune responses, thereby hindering the desired therapeutic outcome." (PMID 39267764, 2024). "In line with IL-2, IL-15 stimulates the proliferation of T and NK cells and could be used as anti-tumour drug with successful anti-tumour effects." (PMID 39315059, 2024). "In addition, combination of IL-2 with PD-1/L1 pathway blockade shows vastly improved anti-tumor efficacy over either monotherapy in preclinical tumor models." (PMID 39114660, 2024). "In summary, this study highlights the favorable clinical diagnostic value of IL-2 in patients with PDAC for the first time and confirms that IL-2 can enhance the efficacy of DC-based tumor vaccines both in vitro and in vivo, providing a promising new approach for PDAC immunotherapy." (PMID 38554155, 2024). "Therefore, the tumor-specific T cells can likely effectively compete with Treg for the available IL-2/CD25 fusion protein, resulting in improved anti-tumor responses." (PMID 39114660, 2024). "Also, Erb-IL-21 presented much lower toxicity than Erb-IL-2, even at high doses and intraperitoneal treatment with Erb-IL-21 limited the tumor growth in well-established tumor models (MC38-cEGFR, B16-cEGFR, and Ag104Ld-cEGFR)." (PMID 38638431, 2024). "The enrichment of IL-6/JAK-STAT3 and IL-2/STAT5 signaling pathways in low SIGLEC9 expression suggests that lower SIGLEC9 levels may activate pro-inflammatory pathways that support an anti-tumor immune response by enhancing cytotoxic T cell activity." (PMID 39727942, 2024). "Alternatively, the CRISPR/Cas9 system has been used to upregulate the expression of chemokine receptors such as CXCR2 and IL-2 on NK cells, thereby leading to increased migration to tumor sites, enhanced proliferation and improved cell killing in a preclinical colon cancer model." (PMID 38443448, 2024). "However, IL-2 monotherapy has notable limitations, including a short serum half-life, low tumor accumulation before systemic toxicity limits dose, and life-threatening adverse events at high doses." (PMID 38910324, 2024).
tumor (continued). "In contrast with tumor antigen targeting, another group demonstrated systemic immune activation contributing to the efficacy of combining hypofractionated radiation therapy with an IL‐2/anti‐IL‐2 complex." (PMID 38317590, 2024). "Still, the results showed that when DPP7 expression in tumor cells was elevated, the cytotoxic function of activated Jurkat cells was inhibited, leading to decreased secretion of the immune cytotoxicity marker IL-2 on the one hand, and decreased viability of Jurkat cells on the other hand." (PMID 39247602, 2024). "Ulrike Stein confirmed that after transducing tumor cells, IL2 and TNF modify treatment resistance." (PMID 38032489, 2024). "Studies have shown that IL-2 and IL-15 induce the expression of CD107a (degranulation marker) on γδ T cells and give these cells their tumor cell-killing ability and that exogenous IL-2 and IL-15 also enhance the effector functions (especially degranulation/cytotoxic potential) of γδ T cells." (PMID 38515134, 2024). "The research highlights the necessity of a multifaceted approach, incorporating a tumor-antigen-targeting antibody, a modified interleukin-2 with extended half-life, anti-PD-1, and a potent T cell vaccine, to effectively mobilize both innate and adaptive immune mechanisms against the tumor." (PMID 38646546, 2024). "The major changes seen with TPV/Δ66R/mIL-2-treated samples compared to RC is that the capsule increased in thickness and had more immune cells infiltrating the capsule as well as the tumor body, likely due to the adaptive immune system activation following interleukin-2 signaling." (PMID 38787254, 2024). "T-cell-based therapy is comprised of TILs, which are extracted from the tumor, activated ex vivo, expanded and reinfused in the patient along with immune enhancing adjuvants, such as interleukin-2 (IL-2), to induce a durable immunological response against the tumor cells." (PMID 38279265, 2024). "The immunotherapeutic application of interleukin-2 (IL-2) in cancer treatment is limited by its off-target effects on different cell populations and insufficient activation of anti-tumor effector cells at the site of the tumor upon tolerated doses." (PMID 38337114, 2024). "Moreover, IL-2 exhibits its antitumor efficacy within a confined subset of patients with antigenic tumor types, such as malignant melanoma or renal cell carcinoma." (PMID 39218928, 2024). "Inhibiting the PD-1/PD-L1 pathway can significantly boost the infiltration of CD4+ and CD8+ T cells in tumor cells, and effectively regulate the expression of a range of immune-related factors such as IL-2, IFN-γ, and TNF-α, thereby strengthening the body's anti-tumor immune function." (PMID 38312647, 2024). "IL-2 is a critical pro-inflammatory factor because it promotes the expansion of T cells, the enhancement of natural killer (NK) cells, and the strengthening of the anti-tumor immune response." (PMID 38790680, 2024). "Therefore, we treated WT and KO tumor–bearing mice with IL-2–blocking Abs (clones S4B6-1 and JES6-1)." (PMID 38787791, 2024). "Hence, one of the potential improvements in the production of therapeutic T cells would be to reassess the role of IL-2 in the generation of T cells that are efficient in killing tumor cells and that will persist as memory cells once transferred in vivo." (PMID 38510150, 2024). "IL-2-N88D by itself has modest anti-tumor activity as monotherapy." (PMID 39114660, 2024). "The pro‐inflammatory effects of SRT on tumor infiltrating myeloid cells described by others could be responsible for very efficient tumor eradication in our colon model when combined with either ICK or IL‐2‐Fc." (PMID 38317590, 2024). "The ambiguity of immuno-stimulatory T-helper (TH) cell type 1 (TH1-type) cytokines, including TNF-α, IFN, IL-2, IL-12, etc., lies in the fact that they can induce cell-mediated immunity and tumor suppression; still, they can also act as pro-inflammatory players." (PMID 38541074, 2024).
tumor (continued). "However, prolonged exposure to tumor cells appears to necessitate IL-2 supplementation for the restoration of their cytotoxic activity." (PMID 39253082, 2024). "The extracted lymphocytes are then expanded in vitro using a culture medium with IL-2, tested for reactivity against autologous tumor cells, selecting the most reactive lymphocytes, and finally incubating them with anti-IL2 and anti-CD3 antibodies before infusion back into the patient." (PMID 39202970, 2024). "Here we report that prostaglandin E2 (PGE2), a known negative regulator of immune response in the tumour microenvironment, is present at high concentrations in tumour tissue from patients and leads to impaired IL-2 sensing in human CD8+ TILs via the PGE2 receptors EP2 and EP4." (PMID 38658764, 2024). "Multiple studies demonstrated that IL-2 was able to slow the progression of solid tumors in both animals and humans; this established evidence that the immune system has the capacity to respond to tumor cells." (PMID 39682188, 2024). "IL-2 is considered an effective treatment option for activating the anti-tumor immune response." (PMID 38361933, 2024). "Additionally, IL-21 in combination with IL-2 and IL-15 was used to obtain the central memory tumor infiltrating T-cells from patients with glioblastoma and pancreatic tumors." (PMID 38638431, 2024). "Thus, to deliver IL-2 specifically to tumor sites, the IL-2-inducing synNotch circuit was developed and coupled with CAR T cells." (PMID 38491394, 2024). "In the tumor microenvironment, the IL2 STAT5 signaling pathway can induce CD8+ T cell exhaustion." (PMID 39926600, 2024). "Low serum levels of PGE2 (<6.5) and IL-6 (<45.8) were significant predictors of longer survival in dogs with anti-PD-L1 therapy (p = 0.033 and 0.031, respectively), whereas IL-2 and IL-6 predicted tumour response to c4G12 treatment (p = 0.030 and 0.013, respectively)." (PMID 38893123, 2024). "Mechanistically, pretreatment with TDE may assist tumour growth by preventing NK cell activation by IL‐2 and the cytotoxic response of these cells to tumour cells." (PMID 39659020, 2024). "Finally, the pro-tumor immunosuppression exerted by MDSCs, an essential contributor to prostate cancer along with NK, androgens, and IL-2, have been included to explore different immunotherapies." (PMID 39598584, 2024). "Moreover, blockade of the PGE2 receptors EP2 and EP4 (EP2/EP4) with small molecule antagonists abrogated the suppressive effect of PGE2 on human TIL expansion from tumour tissue in response to IL-2 ex vivo." (PMID 38658764, 2024). "Numerous clinical trials have demonstrated that IL-2 has toxic effects and induces Tregs proliferation, which may compromise the anti-tumour response." (PMID 38475858, 2024). "Furthermore, some natural products can inhibit immunosuppressive factor secretion: IL-10, TGF-β; promote anti-tumor factor secretion: IL-2, IL-5, IL-6, IL-12; reduce immunosuppressive immune cells: Treg, M2 microphage; increase anti-tumor CD8+ T-cells." (PMID 38426097, 2024). "Depletion of IL2 production in iCCA patients could compromise its anti-tumor effect by attenuating the anti-tumor functions of CD8+ and NK cells, resulting in tumor progression." (PMID 38672199, 2024). "Therefore, it is essential to comprehend mechanistic barriers to IL-2 sensing in the tumour microenvironment to implement strategies to reinvigorate IL-2 responsiveness and T cell antitumour responses." (PMID 38658764, 2024). "ortho-IL-2 does not lead to the activation of NK cells or systemic activation of T cells in mouse models and this data supports the idea that restricting the activity of IL-2 to tumor-antigen specific T cells via other engineering strategies can deliver significant anti-tumor efficacy." (PMID 39114660, 2024).
tumor (continued). "The autologous TILs for adoptive T-cell therapy are prepared by culturing a resected tumor specimen in a high concentration of recombinant interleukin-2 (IL-2), along with IL-15 and IL-21 if necessary, then selecting and expanding them in vitro and transferring them back to the patient." (PMID 39406966, 2024). "Without genetic modification, ACT with TILs (TIL-ACT) first extracts the infiltrating lymphocytes from the patients’ tumor tissues through biopsy or surgery, and then expand them in vitro with IL-2 stimulation, followed by infusion of TILs back into the same patients for treatment." (PMID 38685033, 2024). "Interleukin-2 (IL-2), a growth factor within the immune system, contributes to regulating the activity of white blood cells, participating in processes such as antibody response, tumor surveillance, and hematopoiesis." (PMID 38542875, 2024). "All GLUT1-T, TFAM-T, and GLUT1/TFAM-T cells demonstrated significantly increased gene expression by 4.1-fold, 2.2-fold, and 6.5-fold, respectively, of IL-2, a key cytokine known to promote T cell proliferation by preventing their exhaustion and overcoming tumor immunosuppressors." (PMID 39457563, 2024). "Finally, fourth-generation CARs consist of engineered cells to self-produce cytokines such as IL-2, IL-15, or IL-12, thereby enhancing their proliferation, migration, and activation towards tumor cells." (PMID 39339180, 2024). "Additionally, replacing IL-2 with IL-7 and IL-15 in the culture media showed beneficial effects for the long-term survival and anti-tumor function of UCAR-T cells." (PMID 39906740, 2024). "The administration of IL-2 has been correlated with an elevation in the concentration of soluble IL-2 receptor in patient serum, indicative of a potential enhancement in immune system function aimed at combating tumor growth." (PMID 39267764, 2024). "Immune cell exhaustion in TME is characterized by persistent tumor antigens stimulation, reduced proliferation capacity, enhanced inhibitory receptor expression, and decreased production of effector cytokines such as IL-2, TNFα, or IFN-γ." (PMID 38533507, 2024). "Furthermore, tanshinone IIA also had an anti-tumor effect on stressed mice, which increased the thymus index and improved the immune function by increasing the expression of interleukin-2 (IL-2) and IL-2R." (PMID 38542838, 2024). "Notably, an IL-2Rα-biased agonist upregulated CD25 expression on tumor-specific T cells, and tumor-specific CD8 + T cells became more susceptible to the agonist via positive feedback and restored the IL-2 signature." (PMID 39218982, 2024). "Because MHC-1 antigen presentation deficiency is a common cancer immune escape mechanism, combining tumor-targeting antibodies with IL-2 mRNA restored CD8+ T cell neoantigen immunity in MHC class I-deficient tumors that were otherwise resistant to immune-, chemo-, and radiotherapy." (PMID 39399167, 2024). "Additionally, conducting trials to explore the synergistic effects of NK cell therapy with cytokines (e.g., IL-2, IL-15) or other immune stimulants to boost NK cell activity and sustain anti-tumor responses will provide beneficial outcomes." (PMID 39161385, 2024). "This immunotherapy approach involves isolating TILs from the patient’s tumor, expanding them ex vivo with the assistance of recombinant IL-2 (rIL-2), and re-introducing amplified TILs into the patient to proliferate, recognize, and effectively eliminate the tumor cells." (PMID 39308869, 2024). "Regarding IL-2, this cytokine seems to have a dual effect on the tumor immune microenvironment." (PMID 39199571, 2024). "Tumor-promoted Th2 polarization can suppress T cell anti-tumor response by secreting IL-4, IL-5, and IL-10; in fact, untreated or progressive BC is associated with lower levels of IFN-γ and IL-2 and higher levels of Th2 cytokines." (PMID 39682686, 2024).
tumor (continued). "The main method employed with tumor infiltrating lymphocytes (TILs) is an adoptive cell therapy, which consists of extracting lymphocytes from the tumor place and culture them in vitro while adding different stimuli, such as IL-2, and finally infusing them in the same patient (autologous treatment)." (PMID 38256268, 2024). "Interleukin-2 (IL-2) is a potent cytokine that stimulates the proliferation and activation of cytotoxic T-cells and natural killer cells, enhancing their ability to recognize and eliminate tumor cells." (PMID 38558795, 2024). "ACT protocols employ either tumour-infiltrating lymphocytes (TILs) grown out from tumours in the presence of interleukin-2, or chimeric antigen receptor (CAR)-T cells, which are genetically engineered T cells expressing a synthetic receptor that redirects cytotoxicity towards target antigens." (PMID 39399500, 2024). "NP-mediated delivery of IL-2 at the tumor site has been employed to enhance T cell activity." (PMID 39030582, 2024). "A comparison of clinical data for IL-2 modalities that have been well studied in both i.v. and i.t. administration settings indicates that either mode of administration can elicit significant anti-tumor efficacy at overlapping doses." (PMID 39252938, 2024). "CD4+ T helper 1 (Th-1) cells also mediate an anti-tumor response through the secretion of proinflammatory cytokines such as IL-2, TNF⍺, and IFN-γ, which promotes not only T-cell priming and CTL cytotoxicity but also the anti-tumoral activity of macrophages and NK cells." (PMID 38254796, 2024). "Also enriched in this cluster was the natural killer triggering receptor NKTR, associated with IL-2 activation, and AAK1, implicated in chemokine receptor expression and trafficking to the tumor microenvironment." (PMID 38566989, 2024). "The decreased IL-2 production suggests that exogenous IL-2 may need to be administered simultaneously with bryostatin-1 to achieve optimal anti-tumor activity." (PMID 39877358, 2024). "For IL-2, although it is a cytokine that activates the immune environment and has been proven to promote the proliferation and killing of T cells in anti-tumor immunity, and has been approved for anti-tumor therapy at present." (PMID 39003253, 2024). "Via restoring an imbalanced immune system, parasites and their antigens were able to stimulate the MyD88 pathway and release robust pro-inflammatory cytokines such as INF-γ, TNF-α, IL-1, IL-2, IL-12, and others, thus creating an immunostimulant environment that is hostile to tumor cells." (PMID 39367471, 2024). "DCs and CD8+ T cells secrete IL-2, which can also affect the anti-tumor effect of CD8+ T cells." (PMID 39372416, 2024). "IL-2 is noteworthy as it plays a role in regulating the neuroendocrine system and the secretion of hormones in the gastrointestinal tract; it is also a means of inducing an anti-tumor response during tumor growth and progression." (PMID 39451760, 2024). "IL-2, while supporting CD8+ expansion, also acts upon CD4+ Tregs, which may in turn limit the net anti-tumor benefit of administering IL-2 alone." (PMID 38928238, 2024). "We hypothesized that excessive IL-2 signaling may override Treg-mediated suppression of tumor-reactive CD8+ T cells as well." (PMID 36705564, 2023). "Preserved eggs also significantly up‐regulated IL‐2 expression, showing anti‐tumor effects." (PMID 37823098, 2023). "These IL‐2 antagonists could be used in cancer immunotherapy to repress T reg activities in the tumour." (PMID 35246947, 2023). "In conclusion, CPG administration could remarkably inhibit the transplanted tumor growth in mice with an inhibitory ratio of 45.37% and significantly improve the expression of IL-2, IFN-γ, and TNF-α." (PMID 37958581, 2023). "Furthermore, this antitumor efficacy was boosted by combination treatment with NDV-expressing IL-2, which showed complete tumor regression in 90% of the mice." (PMID 37629483, 2023).